HNRNPA2B1 (heterogeneous nuclear ribonucleoprotein A2/B1)
Diseases named in the same sentence as HNRNPA2B1 in open-access papers (continued):
Sharing a sentence is not in itself a finding about the gene and the disease.
acne (1 paper, 2025). An inflammatory process of the sebaceous glands which is characterized by comedones, nodules, papules and/or pustules on the skin. "For instance, elevated HNRNPA2B1 expression could serve as a diagnostic indicator in acne lesions, enabling personalized interventions targeting RNA processing pathways." (PMID 41614864, 2025). "For example, small-molecule inhibitors targeting HNRNPA2B1-mediated RNA processing could suppress inflammatory cytokine production, offering a precision medicine approach to acne." (PMID 41614864, 2025). "Clinical cohorts with diverse acne severities and C. acnes phylotypes could enhance translational relevance, while CRISPR–based gene editing of HNRNPA2B1 or RBM39 in skin models could clarify their causal roles in inflammation and comedogenesis." (PMID 41614864, 2025). "Central to our findings are the hub genes HNRNPA2B1, HNRNPM, and RBM39, identified through the protein–protein interaction (PPI) network analysis as key regulators of acne pathogenesis." (PMID 41614864, 2025). "Targeting HNRNPA2B1–mediated RNA processing or CLR signaling could lead to precision therapies, improving acne management and minimizing recurrence." (PMID 41614864, 2025).
atrial fibrillation (1 paper, 2023). A disorder characterized by an electrocardiographic finding of a supraventricular arrhythmia characterized by the replacement of consistent P waves by rapid oscillations or fibrillatory waves that vary in size, shape and timing and are accompanied by an irregular ventricular response. "Five feature m6A regulatory genes, ZC3H13, YTHDF1, HNRNPA2B1, IGFBP2, and IGFBP3, were determined (p < 0.05) to establish a nomogram model that can predict the incidence of atrial fibrillation with the RF model." (PMID 37435047, 2023).
cervical squamous cell carcinoma (1 paper, 2022). A squamous cell carcinoma arising from the cervical epithelium. "The results showed that the expressions of WTAP were downregulated; and the expressions of four m6A-RMRs such as HNRNPA2B1, IGF2BP2, FMR1, and HNRNPC were upregulated in patients with preinvasive and invasive cervical squamous cell carcinomas compared with normal controls." (PMID 35211628, 2022).
co-infection (1 paper, 2023). "The results indicate that the expression of hnRNPA2B1 is associated with HBV and HCV co-infection." (PMID 38017546, 2023). "Collectively, the results indicate that the higher expression of hnRNPA2B1 is correlated to a more advanced clinical stage and a poorer prognosis of HCC patients, as well as HBV and HCV co-infection." (PMID 38017546, 2023).
colitis (1 paper, 2023). Inflammation of the colon. "Overall, these results showed that hnRNPA2B1 haplo-insufficiency protected mice from DSS-induced colitis." (PMID 37049395, 2023). "We showed that hnRNPA2B1 mRNA levels were increased in colon in dextran sodium sulfate (DSS)-induced colitis mice and in epididymal white adipose tissue (eWAT) and spleen of high-fat-diet (HFD)-induced obese mice." (PMID 37049395, 2023).
colorectal adenocarcinoma (1 paper, 2022). The most common type of colorectal carcinoma. "The levels of hnRNPA2B1/C/D/F were upregulated in colorectal adenocarcinoma tissues with certain fold changes." (PMID 35875075, 2022). "In our work, we found that the expression levels of hnRNPA2B1/C/D/F were upregulated in colorectal adenocarcinoma tissues." (PMID 35875075, 2022). "Immunohistochemical staining revealed that hnRNPA1, hnRNPA2B1, hnRNPC, hnRNPK, hnRNPR, and hnRNPU are overexpressed in colorectal adenocarcinoma." (PMID 35875075, 2022). "Furthermore, the expression levels were positively correlated with each other, which revealed that the hnRNPA2B1/C/D/F network was involved in colorectal adenocarcinoma carcinogenesis." (PMID 35875075, 2022). "By using IHC staining of 10 human colorectal adenocarcinoma specimens, we confirmed that hnRNPA1, hnRNPA2B1, hnRNPC, hnRNPK, hnRNPR, and hnRNPU were mainly localized in the nucleus and had higher expressions in colorectal adenocarcinoma tissues compared with adjacent normal tissues (ANT)." (PMID 35875075, 2022).
epilepsy (1 paper, 2024). A brain disorder characterized by episodes of abnormally increased neuronal discharge resulting in transient episodes of sensory or motor neurological dysfunction, or psychic dysfunction. "A smaller subgroup of pTau interactors (13 proteins) were significantly increased in epilepsy, including multiple proteins associated with regulation of mRNA splicing (HNRNPA2B1, HNRNPK, NCL)." (PMID 38289539, 2024).
essential tremor (1 paper, 2014). A relatively common disorder characterized by a fairly specific pattern of tremors which are most prominent in the upper extremities and neck, inducing titubations of the head. "We sequenced the exons coding the NES domains of five RNA-binding proteins (TARDBP, hnRNPA2B1, hnRNPA1, TAF15 and EWSR1) that have been previously implicated in neurodegeneration in a series of 257 essential tremor (ET) cases and 376 healthy controls." (PMID 25375143, 2014).
Hypertension (1 paper, 2023). The presence of chronic increased pressure in the systemic arterial system. "Mechanistically, Alivec binds tropomyosin 3 (Tpm3) and heterogeneous nuclear ribonucleoprotein A2/B1 (Hnrnpa2b1) to regulate chondrogenic transformation of VSMCs implicated in vascular dysfunction and hypertension." (PMID 36672953, 2023).
inflammatory bowel disease (1 paper, 2025). A spectrum of small and large bowel inflammatory diseases of unknown etiology. "Moreover, in inflammatory bowel disease, HNRNPA2B1 has been confirmed to affect the infiltration of inflammatory factors by regulating the balance of T cells, thereby causing damage to epithelial cells." (PMID 41244818, 2025).
influenza (1 paper, 2024). An acute viral infection of the respiratory tract, occurring in isolated cases, in epidemics, or in pandemics; it is caused by serologically different strains of viruses (influenzaviruses) designated A, B, and C, has a 3-day incubation period, and usually lasts for 3 to 10 days. "Similarly, hsa-miR-5003-3p, EP300, Valproic Acid, Influenza, and ELAVL1 have interactive relationships centered around EIF2AK2, while hsa-miR-6893-3p, EP300, Calcitriol, Influenza, and HNRNPA2B1 exhibit interactive relationships centered around OASL." (PMID 38601162, 2024).
Insulin resistance (1 paper, 2025). Increased resistance towards insulin, that is, diminished effectiveness of insulin in reducing blood glucose levels. "AXL also interacted with several other miRNAs related to DN: miR-499a and heterogeneous nuclear ribonucleoprotein A2B1 (hnRNPA2B1), as well as its predicted interaction with miR-363 that was related to insulin resistance." (PMID 41233312, 2025).
insulinoma (1 paper, 2024). "HNRNPA2B1 is an RNA-binding protein involved in many post-transcriptional RNA regulation processes that has been shown to be differentially expressed upon glucose exposure in human EndoC-βH1 cells and to regulate intracellular and secreted insulin content in mouse insulinoma MIN6 cells." (PMID 38967666, 2024).
keloid (1 paper, 2025). An irregularly shaped, elevated mark on the skin caused by deposits of excessive amounts of collagen during wound healing. "Then they constructed a keloid diagnostic Lasso model based on 5 genes and divided keloid samples into high-risk and low-risk groups, showing that m6A regulators ALKBH5, FTO, and HNRNPA2B1 were upregulated in the high-risk group, while YTHDF2 was downregulated." (PMID 40860194, 2025).
mucinous stomach adenocarcinoma (1 paper, 2021). "HnRNPA2B1 overexpression was observed in all types of GC while most hnRNPA2B1 amplification was found among mucinous stomach adenocarcinoma." (PMID 34044823, 2021). "Among the 37 available cell lines, hnRNPA2B1 was highly expressed in mucinous stomach adenocarcinoma cell line (HGC-27), poorly differentiated adenocarcinoma cell lines (NUGC-3, SNU-5, SNU-3) and small cell gastrointestinal carcinoma cell lines (ECC10 and ECC12)." (PMID 34044823, 2021). "Again, the two mucinous stomach adenocarcinoma cell line HGC-27 and MGC-803 showed higher hnRNPA2B1 expression, which were taken for functional studies." (PMID 34044823, 2021).
myelodysplastic syndrome (1 paper, 2021). A clonal hematopoietic disorder characterized by dysplasia and ineffective hematopoiesis in one or more of the hematopoietic cell lines. "The alternative splice alterations of HNRNPA2B1 influenced the development and adverse outcome in myelodysplastic syndromes." (PMID 34295818, 2021).
nasopharyngeal carcinoma (1 paper, 2021). A carcinoma arising from the nasopharyngeal epithelium. "miR-146b-5p overexpression retards cell proliferation and facilitates cell apoptosis in nasopharyngeal carcinoma by regulating HNRNPA2B1." (PMID 34381502, 2021).
osteoporosis (1 paper, 2024). A condition of reduced bone mass, with decreased cortical thickness and a decrease in the number and size of the trabeculae of cancellous bone (but normal chemical composition), resulting in increased fracture incidence. "Despite these limitations, we believe that our study provides important new insights into the role of the melatonin/hnRNPA2B1 pathway in microgravity-induced bone loss and osteoporosis." (PMID 39329924, 2024).
ovarian serous cystadenocarcinoma (1 paper, 2021). A malignant serous cystic epithelial neoplasm arising from the ovary. "The expression of YTHDF1, HNRNPC, IGF2BP1, VIRMA, and HNRNPA2B1 was significantly positively correlated with the ovarian serous cystadenocarcinoma (OV) tumor stem cell score (based on DNA methylation) (DNAss)." (PMID 34150845, 2021).
ptosis (1 paper, 2022). The drooping of the upper eyelid. "Here we describe a distinct phenotype of early-onset myopathy caused by specific heterozygous HNRNPA2B1 frameshift mutations clinically manifesting with progressive muscle weakness, ptosis, ophthalmoplegia, dysphagia, and variable degrees of respiratory insufficiency." (PMID 35484142, 2022). "In addition, ptosis, ophthalmoparesis, and dysphagia were absent in the reported HNRNPA2B1 missense (D290V) family, whereas these were consistent phenotypic features within our patient cohort, further differentiating these distinct HNRNPA2B1-related phenotypes." (PMID 35484142, 2022).
Salmonella Infections (1 paper, 2025). Infections with bacteria of the genus SALMONELLA. "Following Salmonella infection, the HNRNPA2B1-deficient mice succumbed earlier to infection and displayed higher bacterial burden and lower cytokine production indicative of failure to clear the pathogen." (PMID 40414614, 2025). "HNRNPA2B1-deficient mice showed opposite effects in vivo in response to LPS-induced endotoxic shock versus Salmonella infection." (PMID 40414614, 2025). "In conclusion, our data demonstrates that HNRNPA2B1 is essential for optimal macrophage function, particularly in the context of intracellular bacterial restriction in the case of Salmonella infection." (PMID 40414614, 2025).
steatosis (1 paper, 2022). Increased lipid within the cytoplasm of cells. "RBM15, YTHDC2, HNRNPC, HNRNPA2B1, and EIF3H were related to steatosis." (PMID 36120320, 2022).
urothelial carcinoma (1 paper, 2022). A malignant neoplasm derived from the transitional epithelium of the urinary tract (urinary bladder, ureter, urethra, or renal pelvis). "This study confirmed the prognostic value of FMR1 and HNRNPA2B1, and constructed a nomogram for individualized prediction of the response to atezolizumab in patients with urothelial carcinoma, which may aid in making treatment strategies." (PMID 36189296, 2022).
ZIKV infection (1 paper, 2017). "In the list of RNA processing and transport GO terms, we found Heterogeneous Nuclear Ribonucleoprotein A2/B1 (HNRNPA2B1), involved in pre-mRNA processing, underwent AS after ZIKV infection, where the second exon of HNRNPA2B1 was skipped." (PMID 29116029, 2017).
tumor (165 papers, 2007 to 2026). "We also explored the association of HNRNPA2B1 expression with other RNA modification patterns as well as tumor stemness." (PMID 39268079, 2024). "GO analysis indicated that hnRNPA2B1 preferentially regulated the translation‐related genes implicated in metabolic processes and tumor invasion." (PMID 38887155, 2024). "This included analyzing the association of HNRNPA2B1 expression with prognosis, tumor mutation burden (TMB), microsatellite instability (MSI), immune response, and immune cell infiltration of individual tumors." (PMID 39268079, 2024). "HNRNPA2B1 amplification correlates with a higher gene expression observed in several cancers and is associated with tumor progression and poor prognosis." (PMID 37039257, 2023). "Recently, abnormal HNRNPA2B1 expression has been discovered in various disease states and linked closely to tumor progression." (PMID 36401285, 2022). "Our analyses revealed that the expression of HNRNPA2B1 was upregulated in tumor and associated with decreased survival rate." (PMID 34917507, 2021). "Forced overexpression of c-myc greatly promoted tumor progression, which was partially compromised by hnRNPA2B1 deficiency and completely abrogated by VHLα." (PMID 32826868, 2020). "Except for UCHL1 and HNRNPA2B1, we found that the high transcriptional levels of the rest of the selected genes are associated significantly with a decrease in tumor burden." (PMID 31551755, 2019). "We further discuss studies associating HNRNPA2B1 with immune-metabolic phenotypes and therapy response, including tumor acidosis, ferroptosis-related pathways, immune evasion, and altered sensitivity to chemotherapy, radiotherapy, endocrine therapy, and targeted treatments." (PMID 42292447, 2026). "In glioma, the circular RNA of exon-encoded origin by Nei Like DNA Glycosylase 3 (circNEIL3) is packaged into exosomes by hnRNPA2B1 and transmitted to infiltrated tumor-associated macrophages, conferring the immunosuppressive ability, which will support and promote tumor progression." (PMID 40699709, 2025). "As a tumor-related gene, HNRNPA2B1 is associated with tumor progression." (PMID 34631545, 2021). "In CAFs, its loading into exosomes is mediated by hnRNPA2B1, enabling its transfer to adjacent tumor cells." (PMID 42088439, 2026). "By observing the level of HNRNPA2B1 in several cellular subtypes, the data revealed that the level of HNRNPA2B1 in NSCLC tissue was higher in tumor cells than that in normal tissue." (PMID 41271615, 2025). "Analysis revealed that 5 of the 20 abundant tumor-exclusive HLA class II peptides originate from HNRNPA2B1, a ribonucleoprotein." (PMID 40234091, 2025). "HnRNPA2B1 drives tumor malignancy and plays a crucial role in regulating the transcription, translation, and other processes of important oncogenes." (PMID 40051725, 2025). "In the NSCLC clinical samples, the HNRNPA2B1 levels also increased as comparing to the para-tumor samples." (PMID 41271615, 2025). "Overall, these data indicated that HNRNPA2B1 silencing reduced the tumor growth, and accelerated the IFN-γ and Fe2+ level in vivo." (PMID 41271615, 2025). "Studies indicate that it inhibits tumor cell proliferation by destabilizing HNRNPA2B1 mRNA and suppressing the PI3K-AKT pathway." (PMID 40703632, 2025). "HNRNPA2B1 can promote cell proliferation and prevent apoptosis through various pathways, and it can also promote tumor cell proliferation through mechanisms such as epithelial-mesenchymal transition (EMT) and angiogenesis." (PMID 40703632, 2025). "While tumor cells have been the main focus of studies on HNRNPA2B1, fewer studies have focused on its effects on SMCs, and even less evidence exists regarding its role in ECs." (PMID 40703632, 2025).
tumor (continued). "miR-184-3p was shown to be selectively packaged into exosomes by heterogeneous nuclear ribonucleoprotein A2/B1 (hnRNPA2B1) and to suppress M2 macrophage polarisation, thereby reducing pro-tumour immune responses and metastatic potential." (PMID 41379397, 2025). "Silencing hnRNPA2B1 reduced glycolysis, tumor growth, metastasis, and increased cisplatin sensitivity." (PMID 38887155, 2024). "HNRNPA2B1 is a member of the HNRNP family, which is associated with telomere function, mRNA translation, and splicing, and plays an important role in tumor development." (PMID 39268079, 2024). "This is consistent with the previously reported high expression of HNRNPA2B1 leading to tumor immunotherapy resistance." (PMID 39268079, 2024). "First, we determined the expression levels of HNRNPA2B1 in cancer and normal tissues in a pan-cancer database, which was further validated in matched tumor and paraneoplastic tissues." (PMID 39268079, 2024). "As anticipated, the depletion of hnRNPA2B1 led to a substantial reduction in both tumor volume and weight compared to the control group, rendering the cells hypersensitive to doxorubicin." (PMID 38626369, 2024). "HNRNPA2B1 is differentially expressed in most tumor types and can predict poor clinical staging and survival status." (PMID 39268079, 2024). "The results unveiled that H. pylori‐induced increase in tumor glucose uptake and lactate and pyruvate production was abolished by hnRNPA2B1 knockdown (KD) in GC cells." (PMID 38887155, 2024). "This is consistent with previously reported results on the role of HNRNPA2B1 in the regulation of the immune microenvironment, immunotherapy resistance, and effects on tumor progression." (PMID 39268079, 2024). "To assess the clinical significance of hnRNPA2B1 in patients with GC, we investigated the hnRNPA2B1 expression levels across different SUVmax values, an indicator of tumor glycolytic metabolism measured via PET/CT (18F‐FDG, 18F‐fluorodeoxyglucose) scans in GC." (PMID 38887155, 2024). "The role of hnRNPA2B1 as a nuclear DNA sensor in cancer is currently in the early stages of research but has shown potential anti-tumor benefits." (PMID 38523155, 2024). "HNRNPA2B1 expression was also closely linked to TMB, MSI, tumor stemness, and chemotherapy response." (PMID 39268079, 2024). "HNRNPA2B1 has been shown to exert a pivotal influence on tumor development, formation of TME, antigen-specific antitumor immunity, and maintenance of tumor stemness." (PMID 39268079, 2024). "HNRNPA2B1 was found to be differentially expressed across most tumor types in TCGA's pan-cancer database and was predictive of poorer clinical staging and survival status." (PMID 39268079, 2024). "We also employed IHC assay and immunofluorescence techniques to assess the expression of HNRNPA2B1 in tumor tissues and its localization in tumor cells." (PMID 39268079, 2024). "This correlation suggests that tumors with high HNRNPA2B1 expression are characterized by higher tumor purity, reduced immune cell infiltration, and potentially diminished responsiveness to immune checkpoint therapies." (PMID 39268079, 2024). "Our research contributes further elucidate the mechanism of HNRNPA2B1 in tumor development and provides a theoretical basis for its clinical application." (PMID 39268079, 2024). "Our study provides a strong support for CRNDE/hnRNPA2B1 as a tumor-driver in CRC and a promising therapeutic target for CRC treatment in the future." (PMID 37716979, 2023). "HNRNPA2B1 activation can promote tumor cell growth, and this RNA-binding protein can activate the ERK/MAPK pathway, thereby regulating tumor cell apoptosis." (PMID 37020597, 2023). "In a word, during the proliferation, apoptosis, invasion, and metastasis of a tumor, hnRNPA2B1 can directly regulate the alternative splicing of pre-mRNA and mRNA stability or cooperate with miRNA on mRNA to regulate downstream signaling." (PMID 37546413, 2023).